USP47 (ubiquitin specific peptidase 47)
Diseases named in the same sentence as USP47 in open-access papers (continued):
Sharing a sentence is not in itself a finding about the gene and the disease.
prostate carcinoma (3 papers, 2024). A carcinoma that arises from epithelial cells of the prostate gland. "This study provides evidence that S.C effectively suppresses tumor progression and induces ferroptosis in prostate cancer cells by targeting the ROS/USP47/BACH1/HMOX1 axis." (PMID 38195593, 2024). "This study provides evidence that S.C effectively suppresses tumor progression and induces ferroptosis in prostate cancer cells by targeting ROS/USP47/BACH1/HMOX1 axis." (PMID 38195593, 2024). "Specifically, in prostate cancer, USP47 expression is significantly downregulated compared to normal tissue, and its expression levels correlate positively with infiltrating levels of certain immune cells." (PMID 38832955, 2024). "Our findings indicate a significant downregulation of USP47 expression in prostate cancer when compared to normal tissue." (PMID 38832955, 2024). "This study found that S.C induces ferroptosis by targeting the ROS/USP47/BACH1/HMOX1 axis in prostate cancer cells." (PMID 38195593, 2024). "In this current study, we focused on the role of USP47 in the anti-tumor immune response of prostate cancer." (PMID 38832955, 2024). "Our unpublished data indicate that Usp47 gene knockout in mouse RM-1 prostate cancer cells can lead to accelerated tumor growth." (PMID 38832955, 2024). "Using a syngeneic RM-1 murine prostate cancer cell line, we examined the impact of host USP47 on tumorigenesis." (PMID 38832955, 2024). "More specifically, our study revealed that S.C represses tumor progression and induces ferroptosis in prostate cancer cells by targeting the ROS/USP47/BACH1/HMOX1 axis." (PMID 38195593, 2024). "Importantly, our findings demonstrated a significant downregulation of USP47 expression in prostate cancer compared to normal tissue." (PMID 38832955, 2024). "Herein, we also found that S.C attenuated USP47 expression in prostate cancer cells." (PMID 38195593, 2024). "ROS, especially H2O2, reduce SLC7A11 and GPX4 expression in cervical cancer and prostate cancer; additionally, ROS stimulate BTB domain and CNC homolog 1 (BACH1) degradation by decreasing the expression of ubiquitin carboxyl-terminal hydrolase 47 (USP47), which can deubiquitinate BACH1." (PMID 39584140, 2024).
autoimmune disease (2 papers, 2023 to 2025). A disorder resulting from loss of function or tissue destruction of an organ or multiple organs, arising from humoral or cellular immune responses of the individual to their own tissue constituents. "Furthermore, the significant upregulation of autoimmune disease–associated gene expression in USP47-deficient Tregs was observed in a functional pathway enrichment analysis, indicating a transcriptional defect in USP47-deficient Tregs." (PMID 37788092, 2023). "Treg-specific deletion of USP47 resulted in autoimmune disorders, severe colonic inflammation, and enhanced antitumor immunity in mice." (PMID 37788092, 2023). "Our findings reveal that USP47 directs m6A-dependent metabolic programs to orchestrate Treg homeostasis and suggest novel approaches for selective immune modulation in cancer and autoimmune diseases by targeting of USP47." (PMID 37788092, 2023).
epilepsy (2 papers, 2024 to 2025). A brain disorder characterized by episodes of abnormally increased neuronal discharge resulting in transient episodes of sensory or motor neurological dysfunction, or psychic dysfunction. "ZNF883-induced USP47 expression suppressed NLRP3 ubiquitination and promoted epilepsy by sponging miR-138-5p." (PMID 40307577, 2025). "Moreover, elevated levels of USP47 are correlated with NLRP3 inflammasome activation and the progression of epilepsy." (PMID 40307577, 2025).
myocardial infarction (2 papers, 2021 to 2023). Gross necrosis of the myocardium, as a result of interruption of the blood supply to the area, as in coronary thrombosis. "USP47 is widely involved in tumor development, metastasis, and other processes while performing a more regulatory role in inflammatory responses, myocardial infarction, and neuronal development." (PMID 37740002, 2023). "USP47 and NF-κB expressions were significantly increased during myocardial infarction, and the levels of USP47 and NF-κB were positively correlated." (PMID 34604226, 2021). "In addition, USP47 plays diverse roles in cancers and myocardial infarction by regulating various substrates." (PMID 34604226, 2021). "USP47 also plays a role in inflammatory responses, myocardial infarction, and neuronal development." (PMID 34604226, 2021). "Therefore, USP47 expression may be related to the progression of myocardial infarction." (PMID 34604226, 2021).
nasopharyngeal carcinoma (2 papers, 2021 to 2024). A carcinoma arising from the nasopharyngeal epithelium. "In nasopharyngeal carcinoma cells, USP47 is the target gene of miR-454, and lncRNA KCNQ1OT1 regulates USP47 expression by binding to miR-454, thereby promoting cisplatin resistance." (PMID 34604226, 2021).
breast carcinoma (1 paper, 2021). "Higher USP47 expression was also associated with breast cancer metastasis and a lower survival probability." (PMID 34604226, 2021). "USP47 is overexpressed in multiple cancers, such as CRC and breast cancer, and it may be a valuable biomarker for diagnosis and prognosis." (PMID 34604226, 2021).
breast tumor (1 paper, 2017). "However, our results indicate that patients with high breast tumor expression of USP47 have significantly better relapse-free survival compared to patients with low breast tumor expression of USP47 (HR=0.65; p-value=2.40E-07)." (PMID 28122328, 2017).
colitis (1 paper, 2023). Inflammation of the colon. "We further established a T cell transfer–induced colitis model to test the effect of USP47 on Treg function in vivo." (PMID 37788092, 2023). "Therefore, Treg-specific USP47 deletion exacerbated experimental colitis and boosted antitumor immune responses, indicating that USP47 is indispensable for Treg immunosuppressive functions in vivo." (PMID 37788092, 2023).
colon adenocarcinoma (1 paper, 2021). "The TPM (Transcripts per kilobase of exon model per million mapped reads) of USP47 was significantly reduced in colon adenocarcinoma (n = 275) than the normal tissues (n = 349)." (PMID 34630087, 2021).
colorectal adenocarcinoma (1 paper, 2017). The most common type of colorectal carcinoma. "Immunofluorescence staining of human colorectal tissue microarrays revealed that USP47 is overexpressed in colorectal adenocarcinoma tissues compared with normal adjacent tissues." (PMID 29162839, 2017). "Immunofluorescence staining of human colorectal tissue microarrays revealed that USP47 is markedly overexpressed in colorectal adenocarcinoma compared with normal colon tissues." (PMID 29162839, 2017).
Fanconi anemia (1 paper, 2023). Fanconi anemia (FA) is a hereditary DNA repair disorder characterized by progressive pancytopenia with bone marrow failure, variable congenital malformations and predisposition to develop hematological or solid tumors. "The DUB proteins USP1, OTUB1, UCHL5, USP7, and PSMD14 were reported to contribute to double-strand break repair, USP1 to Fanconi anemia pathway, USP1 and USP7 to translesion repair, USP7 and USP47 to base excision repair, and USP7 and USP45 to nucleotide excision repair." (PMID 37892185, 2023).
glioma (1 paper, 2023). A benign or malignant brain and spinal cord tumor that arises from glial cells (astrocytes, oligodendrocytes, ependymal cells). "Among the selected DUBs significantly linked to the DNA damage repair pathway, the glioma and MB datasets shared several DUBs, including USP1, USP47, UCHL5, and OTUD1, which cover five major DNA damage repair pathways (BER, NER, FA, TLS, DSB)." (PMID 37892185, 2023).
influenza (1 paper, 2013). An acute viral infection of the respiratory tract, occurring in isolated cases, in epidemics, or in pandemics; it is caused by serologically different strains of viruses (influenzaviruses) designated A, B, and C, has a 3-day incubation period, and usually lasts for 3 to 10 days. "Detailed analysis of three proteins, USP47, TNFSF12 and TNFSF12/TNFSF12-13, confirmed that knocking down these proteins resulted in >85% protection from influenza-induced cell death." (PMID 23949218, 2013).
lymph node metastasis (1 paper, 2021). "Besides, studies in patients with CRC have shown that USP47 was expressed more abundantly in tumors than their normal counterparts, and a higher expression of USP47 was positively correlated with a higher probability of lymph node metastasis and predicted a shorter overall survival." (PMID 34604226, 2021).
metastasis (1 paper, 2025). The spread or migration of cancer cells from one part of the body (where they first appeared) to another. "We performed Dunn’s post hoc tests for pairwise comparisons, which revealed pronounced differences in USP47 expression across various GC subgroups, including tumor invasiveness, lymph node metastasis, tumor stage, and tumor grade." (PMID 39998882, 2025).
myocardial ischemia (1 paper, 2021). A disorder of cardiac function caused by insufficient blood flow to the muscle tissue of the heart. "USP47 expression was increased time-dependently in rat H9C2 myocardial ischemia/reperfusion injury model." (PMID 34604226, 2021). "Downregulating USP47 reduced myocardial ischemia-reperfusion injury by inhibiting apoptosis." (PMID 34604226, 2021).
non-small cell lung carcinoma (1 paper, 2025). A group of at least three distinct histological types of lung cancer, including non-small cell squamous cell carcinoma, adenocarcinoma, and large cell carcinoma. "Additionally, USP28-mediated FOXK1 deubiquitination activates the Hippo signaling pathway to regulate cell proliferation and radiosensitivity, while targeting USP47 enhances the efficacy of KRAS G12C inhibitors in mutant non-small cell lung cancer through regulation of c-Myc deubiquitination." (PMID 41488674, 2025).
prostate adenocarcinoma (1 paper, 2024). "Prostate adenocarcinoma showed significant downregulation of USP47 compared to normal tissue." (PMID 38832955, 2024). "To further explore the potential role of USP47 in the anti-tumor response, we focused on prostate adenocarcinoma (PRAD) for additional analysis." (PMID 38832955, 2024).
prostate tumor (1 paper, 2024). "To explore the physiological impact of USP47 on the antitumor immune response, we conducted a comprehensive analysis using a global Usp47 knockout mouse model and a syngeneic RM-1 murine prostate tumor cell line on the C57BL/6 background." (PMID 38832955, 2024).
tumor (22 papers, 2015 to 2025). "Similar to the influence of USP47 depletion on GC tumor cellular phenotype, Snai1 deficiency profoundly inhibited cell proliferation, colony-forming capability, cell migration, and invasion." (PMID 39998882, 2025). "The differential expression patterns of USP47 in various tumors and its association with infiltrating immune cells underscore the significance of its potential as a biomarker for tumor prognosis and as a therapeutic target." (PMID 38832955, 2024). "In our study, we delved deeper into the impact of Usp47 deficiency on T cell populations within the tumor microenvironment." (PMID 38832955, 2024). "To investigate the impact of host USP47 deficiency on tumor growth, we conducted a comprehensive study using both wild-type and Usp47 knockout mice." (PMID 38832955, 2024). "Further research is needed to elucidate the underlying mechanisms by which USP47 influences tumor biology and to explore its therapeutic potential in a broader range of cancer types." (PMID 38832955, 2024). "Collectively, the altered CTL response within the TME due to Usp47 deficiency could impact antitumor immune responses and contribute to changes in tumor growth dynamics." (PMID 38832955, 2024). "The dysregulation of CTL responses within the TME due to Usp47 deficiency could impact the efficacy of antitumor immune responses and contribute to the observed changes in tumor growth dynamics in Usp47−/− mice." (PMID 38832955, 2024). "Additionally, USP47 deficiency resulted in enhanced activation of cytotoxic T lymphocytes (CTLs) and altered T cell subsets within the tumor microenvironment." (PMID 38832955, 2024). "In particular, we provided comprehensive in vitro and in vivo evidence demonstrating the roles of USP47 in promoting GC cell proliferation and invasiveness as well as its marked contribution to tumor growth and metastasis in the mouse models." (PMID 39998882, 2025). "Conversely, USP47 overexpression markedly accelerated tumor growth, yielding larger tumors and higher weights." (PMID 39998882, 2025). "Some tumor tissues displayed higher expression levels of USP47 compared to normal tissues, while others exhibited lower expression levels." (PMID 38832955, 2024). "Assessing the effects of Usp47 knockout on tumor growth and the tumor microenvironment, we made significant findings." (PMID 38832955, 2024). "Considering the central role of antigen-specific T cell responses in anti-tumor immunity, our finding provides a partial explanation for our understanding of increased activation of tumor infiltrated CTLs in Usp47−/− mice." (PMID 38832955, 2024). "This observed phenotype can be attributed to two key factors: a decrease in tumor cell proliferation and an increase in apoptosis, both of which are consequences of host Usp47 deletion." (PMID 38832955, 2024). "The results unveiled distinct expression patterns of USP47 across different tumor tissues and normal tissues." (PMID 38832955, 2024). "The analysis of infiltrating immune cells in the tumor xenografts of Usp47−/− mice revealed an increased presence of specific immune cell populations, including neutrophil granulocytes, macrophages, NK cells, NKT cells, and T cells." (PMID 38832955, 2024). "In this study, we aimed to investigate the potential role of USP47, a deubiquitinating enzyme, in modulating the tumor microenvironment." (PMID 38832955, 2024). "The expression of cleaved caspase 3, a key marker of apoptosis, was notably increased in the tumor xenografts of Usp47−/− mice." (PMID 38832955, 2024). "To further investigate the underlying mechanisms responsible for the reduced tumor burden in Usp47 knockout mice, we turned our attention to examining the levels of cell proliferation and apoptosis in the tumor tissues." (PMID 38832955, 2024).
tumor (continued). "Our analysis revealed a significant increase in the percentage of tumor-infiltrating CD8+ CTLs (CD45+CD3+CD8+) in Usp47−/− mice, indicating a potential enhancement in the antitumor immune response mediated by CTLs." (PMID 38832955, 2024). "USP47 is expressed in various cancers and plays a significant role in tumor development and progression." (PMID 38832955, 2024). "This prompts us to attempt to comprehensively understand the role of USP47 in the host's anti-tumor immune response." (PMID 38832955, 2024). "This study investigates the role of USP47, a deubiquitinating enzyme, in the tumor microenvironment and its impact on antitumor immune responses." (PMID 38832955, 2024). "Recent studies have reported a positive correlation between USP47 expression and tumor-infiltrating Treg cells in colorectal and gastric cancer patients." (PMID 38832955, 2024). "Through bioinformatic analysis, we observed distinct expression patterns of USP47 across various tumors and normal tissues, indicating its involvement in different tumor types." (PMID 38832955, 2024). "Analysis of TCGA database revealed distinct expression patterns of USP47 in various tumor tissues and normal tissues." (PMID 38832955, 2024). "USP47 is a potential oncogenic protein expressed in various tumor types and mediates tumor cell proliferation and tumor progression." (PMID 37788092, 2023). "To confirm the importance of YTHDF1 in the defective suppressive functions of USP47-deficient Tregs, we performed IBD induction and tumor inoculation using 6-week-old WT mice, Usp47fl/flFoxp3-Cre mice, and Usp47fl/flYthdf1fl/flFoxp3-Cre mice." (PMID 37788092, 2023). "USP47 is highly expressed in many tumors and is widely involved in tumor development, metastasis, drug resistance, epithelial-mesenchymal transition, and other processes." (PMID 34604226, 2021). "Because hypoxia-induced USP47 expression enhanced EMT by stabilizing Snail, we investigated the contribution of USP47 to tumor growth and invasion in vivo." (PMID 29162839, 2017). "Effect of USP47 on GC cell proliferation and in vivo tumor growth and metastasis." (PMID 39998882, 2025). "Consistent with in vitro results, USP47 knockdown drastically inhibited tumor growth in vivo." (PMID 39998882, 2025). "Additionally, our investigation reveals that USP47 upregulation potentially contributes to GC pathogenesis and tumor progression via the epithelial-mesenchymal transition (EMT) signaling pathway." (PMID 39998882, 2025). "Furthermore, we identify Snai1 as a deubiquitination target of USP47, explaining USP47-dependent activation of the epithelial-mesenchymal transition pathway and tumor progression." (PMID 39998882, 2025). "Furthermore, USP47 was found to correlate with tumor‐infiltrating Tregs in colorectal and gastric cancer, indicating its potential relevance in the tumor microenvironment and immune modulation." (PMID 40919129, 2025). "This suggests that USP47 may play a crucial role in modulating the recruitment or function of these immune cells within the tumor microenvironment." (PMID 38832955, 2024). "Notably, the lack of host USP47 led to an aberrant increase in CTL activation, suggesting a critical role for host USP47 in modulating antitumor immune cell homeostasis and participating in the anti-tumor process." (PMID 38832955, 2024). "The altered immune cell composition observed in Usp47 knockout tumors may contribute to the observed changes in tumor growth dynamics and the immune response." (PMID 38832955, 2024). "The increased presence of neutrophil granulocytes, macrophages, NK cells, NKT cells, and T cells in Usp47−/− tumors could potentially contribute to the observed reduction in tumor growth and enhanced apoptosis." (PMID 38832955, 2024).